TNF (tumor necrosis factor)
Diseases named in the same sentence as TNF in open-access papers (continued):
Sharing a sentence is not in itself a finding about the gene and the disease.
infection (continued). "Additionally, mRNA levels of pro-inflammatory cytokines including IL-6, TNF-α, IL-1β, and IL-8 were significantly reduced in BALB/cTFE3-/- mice relative to BALB/cTFE3+/+ mice, suggesting a critical role of TFE3 in viral replication and infection." (PMID 39652582, 2024). "Despite the transient defects in leukocyte recruitment in TNF KO mice, bacterial burdens were similar between WT and TNF KO animals across the 28-day infection period and antibiotic administration did not reveal additional changes in bacterial abundance between TNF KO and WT conditions." (PMID 39044282, 2024). "However, because TNF had no impact on bacterial burden during craniotomy infection, this model is suboptimal to pursue this idea further." (PMID 39044282, 2024). "To test these hypotheses, we infected a variety of iBMDM cell lines that lacked individual TLR sensor components and assessed their TNF production under different infection conditions." (PMID 39609397, 2024). "In addition, we showed that M- and ICU-COVID monocytes had reduced responsiveness towards further live Pseudomonas aeruginosa (PAO1 strain) infection, an important pathogen colonizing COVID patients in ICU, as assessed by an impaired secretion of myeloid cytokines (IL-1, TNF, IL-8...)." (PMID 38835759, 2024). "To explore why S. aureus titers were not affected following TNF loss, we first examined whether TNF influenced macrophage, PMN, and G-MDSC responses to S. aureus- the major cellular infiltrates during craniotomy infection." (PMID 39044282, 2024). "Concerning TNF-α, no upregulation was detected in our infection model at all." (PMID 38533334, 2024). "Ripk3D333A/D333A macrophages died at the same rate as wild-type (WT) macrophages in response to TNF plus cycloheximide, TNF plus emricasan, or infection with murine cytomegalovirus (MCMV) lacking M36 and M45 to inhibit caspase-8 and RIPK3 activation, respectively." (PMID 38191748, 2024). "IL-6 and TNF-α did not change significantly up to 8 days after M. gallisepticum strain Rlow infection, except that IL-1 was significantly up-regulated at 3 days post-infection." (PMID 38474071, 2024). "Collectively, while granulocytes augment Lta expression in the context of TNF deficiency, the fact that bacterial burdens were not dramatically altered in TNF, TNFR1, or TNFR2 KO mice indicates that TNF signaling in isolation is not sufficient to alter the course of craniotomy infection." (PMID 39044282, 2024). "The PBS group showed high levels of inflammatory cytokines including IL-6, IL-18, IL-12 p70, IFN-γ, and TNF-α as well as chemokine GMCSF, which may suggest enhanced vascular permeability and increased infiltration of innate immune cells in response to infection in unvaccinated animals." (PMID 38711520, 2024). "Other groups have shown that TNF is essential in fighting off Spn infections, as mice from TNF KO backgrounds and mice treated with anti‐TNF could not control the infection successfully." (PMID 38459711, 2024). "Notably, the initial infection polarizes a Th1-type response through the production of cytokines such as IL-6, IL-12, and IL-23, which results in Th1 cells with a high production of IFN-y and TNF-a cytokines (especially the latter in recurrent infections)." (PMID 38248954, 2024). "Of note, viral clearance in Perforin-/- mice with or without IFN-γ and TNF-α neutralization could be mediated by compensatory mechanisms such as Fas-FasL mediated cytotoxicity as has been shown for a different infection model." (PMID 39392861, 2024). "Interestingly, these reductions in terminal maturation were also observed in naïve NK cells, suggesting that TNF acts on NK cells during development and the changes were not entirely due to infection-induced TNF." (PMID 39543125, 2024). "Thus, we next examined soluble TNF release from neutrophils in the presence and absence of priming and infection." (PMID 38965211, 2024).
infection (continued). "Specific single nucleotide polymorphisms (SNPs), such as PTPN22 rs2476601 and CTLA4 rs3087243, are associated with infection-triggered CFS/ME, while other SNPs, such as IRF5 rs3807306 and TNF rs1799724, have decreased allele frequencies in CFS/ME patients who do not have infection-triggered onset." (PMID 39483544, 2024). "It has been reported that, after infection with G. parasuis, the expression of p38, ERK, and JNK increased in porcine alveolar macrophages (PAMs) via the NF-κB and MAPK signaling pathways, leading to the upregulation of inflammatory cytokines such as IL-1α, IL-1β, IL-6, IL-8, and TNF-α." (PMID 38927100, 2024). "Furthermore, infection of THP-1-derived macrophages with live/heat-killed Fn induced IDO expression in a time- and dose-dependent manner through LPS-mediated induction of the tumor necrosis factor (TNF-α) and IL-6, which are both IDO inducers." (PMID 38448800, 2024). "-Phage-encoded in the M1T1 clone.-Cleaves DNA in neutrophil extracellular traps (NETs).-Suppresses TLR9-mediated IFN-α and TNF-α production, leading to decreased macrophage bactericidal activity.-Weakens the recruitment of dendritic cells by reducing IFN-1 levels at the site of infection." (PMID 38258026, 2024). "The percentage of triple positive polyfunctional CD4+ T cells towards parental spike was slightly higher among patients with prior infection, whereas non-infected patients had slightly higher levels of TNFα+IL-2+ dual positive CD4+ T cells towards spike from BA.4/5." (PMID 38326340, 2024). "The initial response to infection is crucial for pathogen clearance, however, this response spirals into a SIRS, characterized by an excessive release of pro-inflammatory cytokines such as interleukin-1 (IL-1), interleukin-6 (IL-6), and tumor necrosis factor-alpha (TNF-α)." (PMID 39712033, 2024). "However, the lack of changes in bacterial burden in TNF KO animals suggests the involvement of additional signals that dictate S. aureus pathogenesis during craniotomy infection." (PMID 39044282, 2024). "By contrast, the overexpression of circYthdc2 or Linear-FLAG-Ythdc2-170aa both could significantly inhibit the expression levels of interferon IFN1, inflammatory cytokines (TNF-α), and antiviral genes such as myxovirus resistance protein 1 (Mx1), ISG15, and Viperin after SCRV infection." (PMID 38361078, 2024). "Interestingly, despite impaired leukocyte recruitment up to day 14 post-infection in TNF KO animals, this did not translate to altered bacterial burden in any infection compartment analyzed." (PMID 39044282, 2024). "We purport that the reason for the discrepancy between these reports and our own is that in an excessively inflamed or aged host, anti‐TNF treatment reduces the levels of negative homeostatic suppressors so that an effective cell signaling response to infection can occur at the onset." (PMID 38459711, 2024). "Interestingly, infection alone or TNF stimulation before the infection did not alter the baseline glutamate levels in U-87 MG cell supernatants." (PMID 38776344, 2024). "Likewise, and although Leishmania infection of peritoneal inflammatory macrophages results in the production of TNFα, in our model, infection with both species of Leishmania did not promote significant TNFα production." (PMID 39696675, 2024). "Even during infection with flagellin-deficient L. pneumophila, which does not induce NAIP5/NLRC4 activation, we observed significant induction of L. pneumophila-triggered cell death following TNF priming." (PMID 37279255, 2023). "TNF-α protein expression was not significantly different between the infection groups." (PMID 37998345, 2023). "It has been hypothesized that reducing, but not fully blocking, TNF-α production by host cells would alleviate inflammatory responses and improve the outcome of antibiotic treatment during infection." (PMID 37107001, 2023).
infection (continued). "Of the 21 analytes that were evaluated, 9 analytes (angiopoietin, CCL3, CCL5, CCL7, CCL12, CXCL10, and TNF-α) were significantly changed in response to infection in both non-pregnant and pregnant mice, and more robust response was, in general, noted in non-pregnant mice (p < 0.05)." (PMID 38104118, 2023). "In addition, the inflammatory cytokines Interferon-γ (IFN-γ), tumour necrosis factor α (TNF-α), transforming growth factor-β (TGF-β), and Arginase 1 (Arg-1) were significantly upregulated after the TgCtwh3 infection, while glial fibrillary acidic protein (GFAP) was down regulated." (PMID 37651502, 2023). "The present study investigated whether SaaS mediated the secretion of cytokines in vivo, with the interleukin (IL)-1β, IL-6, IL-18, tumor necrosis factor-α (TNF-α), inducible nitric oxide synthase (iNOS) and cyclooxygenase-2 (COX-2) levels in colon after infection examined with ELISA or RT-qPCR." (PMID 37158502, 2023). "Moreover, we found that infection with SADS-CoV induced mRNA expression of inflammatory cytokines such as IL-6, IL-1β, and TNF-α, all of which could be prevented by 17-DMAG." (PMID 36963723, 2023). "Similarly, at 12 h post infection, C1q-treated cells exhibited lower gene expression levels of IL-6 (~ −5-fold), IFN-α (~−1.9-fold), IL-1β (~−4.5-fold), and TNF-α (~−4.4-fold)." (PMID 37376569, 2023). "Cytokines (IL-1β, IL-6, IL-8, TNF-α, IFN-β, IFN-γ, etc.), mainly derived from mononuclear phagocytes and other antigen-presenting cells, play important roles in defending against pathogen infection and in promoting infiltration of inflammatory cells in tissues." (PMID 38053560, 2023). "For example, immunological signatures are altered during severe infection, and levels of a wide range of pro-inflammatory cytokines [such as S100A8/A9, interleukin 1 beta, interleukin 6 (IL-6), IL-8, CXCL10, and tumor necrosis factor alpha (TNFα)] are dramatically increased." (PMID 37936693, 2023). "Pro-inflammatory (IFNγ, IL-6, TNFα), Treg (IL-10, TGFβ1, TGFβ3), Th9 (IL-9), Th17 (IL-17), and Th2 (IL-4, IL-13) cytokines, total IgM and IgG, as well as gene expressions of FoxP3, STAT5+, IFNγ-R1, and ROR alpha+, were measured at day 1, day 7, day 14, day 21, and day 28 post-infection." (PMID 37569646, 2023). "Moreover, we found that infection with SARS-CoV-2 GFP/ΔN induced inflammatory cytokines such as IL-1β and TNF-α mRNA expression, all of which could be prevented by 17-DMAG." (PMID 37011862, 2023). "Furthermore, during infection and cancer, A2AR engagement seems to inhibit via IL-15 signaling blockade, the generation of human CD39+NK cells endowed with a potent degranulation capacity and overexpression of IFNγ and TNFα." (PMID 37753093, 2023). "No significant rise or difference in TNFα titer could be detected over the course of infection, independent of the cell medium (p = 0.2014 (medium P) and p = 0.7619 (medium D)." (PMID 37085774, 2023). "Whole lung tissue was collected 24 h after infection and processed for RT-qPCR to evaluate for relative gene expression of proinflammatory genes IRAK1, TRAF6, NF-κB, IL-6, MIP-2 (murine IL-8 analog), IL-1β, and TNFα as these cytokines outline the pathway along which miR146a functions." (PMID 37765178, 2023). "Importantly, bovine macrophages were herein found not to secrete TNFα in the context of C. burnetii infection, despite of infection-induced mRNA synthesis and the ability to secrete TNFα after LPS stimulation." (PMID 36793725, 2023). "CD8, γδ-T cells (positive for γδ-TCR and γδ-WC1), NKp46, TNF-α, FoxP3, and IL-10 cell labelling were significantly lower in NC than in DL, and the estimated differences between the NC group and the three infection groups were generally similar, though not consistently statistically significant." (PMID 37375536, 2023).
infection (continued). "Treatment with melatonin at 250 μM before and after infection significantly reversed the induction of TLR3 (p < 0.05) and TLR7 (p < 0.01) mRNA levels and suppressed the expression of NF-κB (p < 0.05), COX-2 (p < 0.05) and TNF-α (p < 0.001) induced by JEV infection." (PMID 37055489, 2023). "Our results agreed with this because they showed inhibition of TNF-α and IL-6 production and the absence of stimulation of cytokines that are important in CL control, suggesting that other mechanisms are necessary to control the infection." (PMID 37255095, 2023). "Considering the roles of TNF-α in TB, including macrophage activation, cell recruitment to infection sites, and granuloma formulation, exposure to PM2.5 could increase the risks of both initial infection and reactivation of TB." (PMID 37648454, 2023). "Therefore, anti-cytokine therapy, especially anti-TNFα therapy, may inhibit the viral proliferation of SARS-CoV-2 and reduce infection-mediated organ damage." (PMID 37515185, 2023). "However, this was not the case for TNF, the transcription of which was enhanced by the infection independently of IFNγ." (PMID 37383236, 2023). "TNF signaling also stimulates the production of adhesion molecules, such as intercellular adhesion molecule-1 (ICAM-1) and vascular cell adhesion molecule-1 (VCAM-1), which allow immune cells to adhere to and traverse the endothelial barrier to reach the site of infection." (PMID 37511508, 2023). "Regarding TNF-α, in general, males exhibited higher levels than females, although the increase was not significant; the infection increased the TNF-α concentration in the intact groups; however, DHEA administration did not significantly modify the concentration of this cytokine." (PMID 37628731, 2023). "We observed, upon LdCen−/− infection, enhanced expression of TLR-9 receptor on DCs stimulated NF-κB signaling protein through MyD88-dependent mechanism to produce proinflammatory cytokines such as IL-12 and TNF, which have a protective function during Leishmania infection." (PMID 37111420, 2023). "The infection of murine bone marrow-derived macrophage (BMDM) with RVFV strains ZH501 or MP12 resulted in a lower expression of pro-inflammatory cytokines IFN-β, IFN-γ, TNF-α than after infection with recombinant MP12 with an in-frame deletion of 69% of the NSs gene (rMP12-C13)." (PMID 37764982, 2023). "Indeed, quantification of cytokine production by ELISA revealed a spike in secretion 6 hours post- infection with a doubling in TNF alpha levels and a fivefold increase in IL-6 levels (IL-6 average 90 pg/mL, TNFα 40 pg/mL) that were already back to baseline levels 1 day after infection." (PMID 37830871, 2023). "In addition, after infection with T. gondii, CD4+ T cells and CD8+ T cells secrete inflammatory factors such as TNF-α and IL-1 to stimulate microglia, and interfere with gamma-aminobutyric acid (GABA) and 5-hydroxytryptamine (5-HT) synthesis via the KYNA pathway." (PMID 37077528, 2023). "However, CATH-1 significantly increased the secretion of IL-1β and IL-6 while it did not change the secretion of TNF-α when CATH-1 was incubated with cells at post-infection." (PMID 37605242, 2023). "Treatment with CNP-miR146a four hours after infection resulted in significantly decreased relative gene expression of TRAF6 (p = 0.01), NF-κB (p = 0.003), IL-6 (p = 0.01), MIP-2 (p = 0.005), IL-1β (p = 0.01), and TNFα (p = 0.003) compared to untreated, MRSA-infected lungs." (PMID 37765178, 2023). "Of the two S. parasuis strains, NN1 possessed a higher capacity to induce IL-6, TNF-α, and MCP-1 production by primary astrocytes throughout the experiment, and by BV2 cells at 8 h post-infection, whereas BS26 induced higher IL-6 production by BV2 cells from 18 h post-infection." (PMID 37111486, 2023).
infection (continued). "Tumor necrosis factor-α (TNF-α), interleukin-6 (IL-6) and interferon-γ (IFN-γ) are the most important cytokines involved in inflammation and could induce an innate immune system to manage the infection." (PMID 35606770, 2022). "Furthermore, nucleofected OT-I cells displayed subtle differences in cytokine producing ability on day 7 as compared to NTC OT-I cells, whereas there was a slight decrease in the frequency of IFN-γ+ cells (but not IFN-γ+ TNF-α+ cells) >40 days after infection." (PMID 35844563, 2022). "Researchers observed that moMφ’s infection with virulent Georgia 2007 resulted in downregulated expression of anti-inflammatory IL-10 and upregulated expression of IL-17 and cytokines of TNF superfamily, including FASL, LTA, LTB, TNF, TNFSF4, TNFSF10, TNFSF13B, and TNFSF18." (PMID 35215216, 2022). "However, numerous studies have shown that several pro inflammatory cytokines, including IL-6 and TNFα increase with age in healthy individuals and in the absence of infection." (PMID 35700185, 2022). "Infection and TNF combined (but neither alone) increased succinate levels over baseline." (PMID 35737799, 2022). "The TNF gene in mouse blood samples showed up-regulated expression in the E. canis-infected mice with the absence of rGP19 immunization on day 14 of the post-infection period." (PMID 36006302, 2022). "However, we observed no induction of TNF-α following infection of ARPE-19 or primary retinal pigment epithelial cells with DENV-1 strains, and induction of IL-6 in infected ARPE-19 cells alone." (PMID 35208767, 2022). "Next, PAMPs trigger the production of several proinflammatory cytokines and chemokines, including TNF, IL-6, type-1 IFN, CCL2, CCL3, CCL4, and CXCL10 (IFN-γ-induced protein 10 kDa [IP-10]), which lead to the recruitment of monocytes, macrophages, and T cells to the infection sites." (PMID 35464491, 2022). "The high blood TNF-α levels in patients with tonsil foci infection in PPP and the high cytokine levels produced by the alpha-streptococcal stimulation of excised tonsil mononuclear cells suggest that some individuals are more likely to have increased TNF-α production due to their genetic background." (PMID 35897837, 2022). "Discontinuation of the anti-TNF-treatment resolved the infection without specific therapy." (PMID 36530876, 2022). "Similarly, another study showed high levels of IP10, MCP1, granulocyte colony-stimulating factor (GCSF), Macrophage inflammatory protein-1 alpha (MIP-1α), and TNF-α in patients who required ICU admittance, indicating that the severity of the infection was correlated with the cytokines." (PMID 36584119, 2022). "The infection did not modify the levels of TNFα to this parasite." (PMID 35335632, 2022). "The levels of different cytokines, i.e., IL-12, MCP-1, TNF-α, and MIP-1α, were determined in the THP-1 cell culture supernatants of the uninfected, active, and latent groups at different time intervals, i.e., 0 h, 6 h, 18 h, and 24 h of infection, in the presence of different glucose concentrations." (PMID 36776550, 2022). "In KO male mice, the IKK complex that may be activated indirectly by the TNF is increased at 6 h post-infection with or without rescue." (PMID 35844510, 2022). "No changes were observed in TNF-α mRNA expression 6 h post-infection after treatment with ghA." (PMID 35328462, 2022). "Some studies suggested that system or local infection could increase release of thrombopoietin and different inflammatory cytokines, such as IL-1, IL3 and IL6 and tumor necrosis factor-α, result in increasing thrombopoiesis and lead to the production of younger large platelets in blood circulation." (PMID 35614411, 2022). "Despite the increased number of neutrophils in the lung, we failed to observe a rise in the expression of the pro-inflammatory cytokines, TNFα, IL1β or IL-6, in the lung of aged mice after infection, when compared to the lungs of young-infected mice (data not shown)." (PMID 35392033, 2022).